RSPO1 (R-spondin 1)
Diseases named in the same sentence as RSPO1 in open-access papers (continued):
Sharing a sentence is not in itself a finding about the gene and the disease.
tumor (continued). "Combined treatments involving tumor-specific silencing of Rspo1 combined with non-tumor-specific Rspo1 treatment would be useful, as such treatments could both decrease tumor cell radioresistance and increase normal cell radioprotection." (PMID 25865226, 2015). "It would be interesting to determine whether a tumor therapy dosage window exists between normal tissue radioprotection and tumor cell radioresistance induced by Rspo1." (PMID 25865226, 2015). "Since testis angiogenesis seems to have some similarities with tumour angiogenesis, the role of RSPO1, in tumour progression and vascularisation, could represent a common mechanism used in physiological and pathological angiogenesis." (PMID 25910078, 2015). "Based upon the findings that Rspo1 is protective against radiation-induced gastrointestinal syndrome, we hypothesize that Rspo1 may be involved in the radioresistance of tumor cells to radiation therapy." (PMID 25865226, 2015). "RNA‐seq and Kyoto Encyclopedia of Genes and Genomes (KEGG) pathway analyses revealed that the P2 and LM8 organoids showed enhanced transcriptional regulation of the Wnt and other tumor‐associated pathways, especially the Notch and Jak/Stat pathways, in the medium without RSPO1." (PMID 39601111, 2025). "Together, the findings suggest that RSPO1 may have important links to tumor immunity." (PMID 38962149, 2024). "Importantly, LGR5 and LGR6, and their ligands RSPO1–4, are upregulated in several cancers, lending support to the idea that elevated Wnt signaling may be a driver of tumor formation." (PMID 29416699, 2018). "To further investigate the interaction between RSPO1 expression and the TME, we used the CIBERSORT algorithm to focus on the tumor-infiltrating immune cells of ESCA samples." (PMID 38962149, 2024). "It is important to note that LGR5 expression is decreased in advanced stages of colon cancer; hence, when RSPO1/LGR5 stimulates TGFβ signaling, it leads to the inhibition of tumor growth and induction of apoptosis." (PMID 39183418, 2024). "The biological significance of RSPO1 was further elucidated using KEGG, GO, and GSEA, demonstrating its relevance to pivotal tumor and immune pathways." (PMID 38962149, 2024). "Of note, Rnf43/Znrf3del tumour organoids, but not WT controls, grew long-term (up to passage 10) in the absence of RSPO1, confirming their origin from Rnf43/Znrf3del cells." (PMID 35039505, 2022). "Antral organoids of Mist1-CreERT; Apcflox/flox mice can grow without Wnt3a and R-spondin 1 in culture media only when recombination is induced by tamoxifen, suggesting that the tumor development in these mice is cell-autonomous effect." (PMID 29340033, 2017). "Of note, the finding of macrophage infiltration upon Rspo1 overexpression and Znrf3 deletion is contrary to studies in other systems in which WNT/β-catenin activation has been reported to favor exclusion of infiltrating immune cells from the tumor microenvironment." (PMID 37102205, 2023). "Furthermore, research in the mechanism found PVT1 could target genes such as LASP1, FOXM1, RSPO1, p15, p16, EZH2, TSHR, and NOP2 to promote tumor cell proliferation, migration and invasive capability in vitro." (PMID 29088881, 2017). "Among nonmalignant cell types, RSPO1+ fibroblasts and FOLR2+ macrophages were identified as potential tumor-suppressing populations and POSTN+ fibroblasts and SPP1+ macrophages were identified as tumor-promoting populations." (PMID 38519500, 2024). "Unlike RSPO1-3, RSPO4 has not been identified in almost all kinds of tumor tissues and normal tissues yet." (PMID 36645115, 2023). "Interestingly, little to no expression of RSPO1 and RSPO2 were found in these cell lines, suggesting that their expression in primary tumors was most likely from stromal or other non-tumor cells." (PMID 39065640, 2024).
cancer (54 papers, 2012 to 2026). A tumor composed of atypical neoplastic, often pleomorphic cells that invade other tissues. "Very recently, we have demonstrated that fibroblasts obtained from PPK area of two patients with germline RSPO1 mutations display a cancer-associated phenotype." (PMID 35854363, 2022). "Primary fibroblasts from PPK areas of RSPO1-mutated patients behave as cancer associated fibroblasts (CAFs), which promote collagen contraction and SCC matrix invasion." (PMID 35854363, 2022). "Previously reported genetic and cancer-associated mutations further corroborate the functional significance of the ZNRF3ecto–Rspo2Fu1–Fu2 interface as the generic interaction mode for Rspo1–4 and ZNRF3/RNF43." (PMID 24225776, 2013). "Given that RSPO1 mutations may be molecular targets for cancer treatment, we analyzed ESCA samples from TCGA." (PMID 38962149, 2024). "Further refinement of this matrix risk signature to specifically predict which lesions will progress to cancer identified a minimum 6-gene risk signature of RSPO1, CTHRC1, SPP1, MMRN1, COL10A1, and PRG4 as the most significant matrisomal predictors of premalignant progression with a ROC AUC of 0.99." (PMID 36404344, 2022). "The notion that LGR6 is expressed specifically in a population of stem cells that can give rise to all cell lineages of the skin and that cancer often originates from stem cells suggests that LGR6 may be the underlying receptor for the tumor suppressive role of RSPO1." (PMID 22615920, 2012). "Amplification of RSPO1 signaling induces granulosa cell fate defects and cancers in mouse adult ovary." (PMID 40428299, 2025). "RSPO1 plays a role in the progression of cancers, such as colorectal, breast, liver, glioma, and ovarian." (PMID 38962149, 2024). "The upregulation of Rspo1 upon radiation treatment suggests that the dependence on Rspo1 for survival is amplified in radiotherapy-treated cancer cells." (PMID 25865226, 2015). "We think that these oncogenic features may confer a growth advantage to KRAS-mutant cancer cells under 3D culture conditions, especially in our system, where additional growth factors such as Wnt3a, R-spondin-1, and Noggin were excluded." (PMID 40462147, 2025). "Notably, we avoided using organoid culture media components such as Wnt3a, R-Spondin-1, and Noggin, which are known to influence the molecular subtypes of cancer cells." (PMID 40462147, 2025). "R-spondin-1 facilitates the proliferation, division and metastasis of cancer cells." (PMID 38342791, 2024). "Numerous studies have demonstrated that RSPO1 contributes to cancer progression." (PMID 38962149, 2024). "But recent data shows that RSPO1 is also expressed in other tissues and certain cancer cells." (PMID 34169096, 2021). "Nearly all CRCs harbor activating mutations in the Wnt pathway or fusion of RSPO(R-spondin-1) genes, allowing for the expansion of cancer cells without Wnts and R-spondins, while normal epithelial cells arrest." (PMID 33135109, 2020). "Growth factors for cancer organoid culture include Wnt3A, R-spondin-1, TGF-β receptor inhibitor, epidermal growth factor, and Noggin, but the combination and concentration of these factors added to the media depend on the specific cancer type." (PMID 36713421, 2022).
infection (2 papers, 2016 to 2022). The state of being infected such as from the introduction of a foreign agent such as serum, vaccine, antigenic substance or organism. "In contrast, Rspo3 expression was downregulated 2-fold by day 3 of infection while Rspo1 was downregulated 2-fold by day 6 of infection." (PMID 27046199, 2016). "To determine if the downregulation of Rspo1 and Rspo3 was potentially a compensatory response to the increase in Rspo2 during infection, we assessed R-spondin levels in resistant C3Ou.B6-Cri1 congenic mice at days 3, 6, and 9 post-infection." (PMID 27046199, 2016).
adenocarcinoma (1 paper, 2015). A common cancer characterized by the presence of malignant glandular cells. "To pursue this, we micro-dissected and dissociated adenocarcinomas from Lin28bLo/Let7IEC-KO mice and cultured “tumoroids” from these lesions in medium supplemented with EGF, Noggin, and Rspo1 for enteroid culture." (PMID 26244988, 2015).
gastrointestinal disorders (1 paper, 2026). "This makes RSPO1 a promising candidate for regenerative medicine, particularly in treating gastrointestinal disorders characterized by impaired epithelial repair." (PMID 41568727, 2026). "Consequently, RSPO1 is recognized as a major driver of WNT‐dependent crypt self‐renewal with therapeutic potential for gastrointestinal disorders." (PMID 41568727, 2026).
RSPO1 also shares sentences with these, for which no sentence is quoted: colorectal cancer (9 papers); gastric cancer (5); pancreatic cancer (5); prostate carcinoma (4); Hyperkeratosis (3); mucositis (3); cholangiocarcinoma (2); colorectal tumors (2); Familial adenomatous polyposis (2); glioblastoma (2); inflammatory bowel disease (2); Insulin resistance (2); lung adenocarcinoma (2); ovarian tumor (2); Papillary Thyroid Cancer (2); sarcoma (2); small intestinal tumor (2); alopecia (1); amyotrophic lateral sclerosis (1); androgen excess (1); Azoospermia (1); chronic kidney disease (1); cognitive decline (1); cognitive deficits (1); colon adenocarcinoma (1); colon polyps (1); colorectal polyps (1); congenital adrenal hyperplasia (1); endometrial cancer (1); epidermal disease (1).
A further 35 diseases each share a sentence with RSPO1 in 1 paper.